TRIP13 (thyroid hormone receptor interactor 13)
Diseases named in the same sentence as TRIP13 in open-access papers (continued):
Sharing a sentence is not in itself a finding about the gene and the disease.
melanoma (4 papers, 2016 to 2024). A malignant, usually aggressive tumor composed of atypical, neoplastic melanocytes. "In this study, we investigated the biological function and the underlying mechanisms of TRIP13 in melanoma." (PMID 36268276, 2022). "TRIP13 overexpression was associated with a malignant phenotype of melanoma, and the interaction of TRIP13 and FLNA activated the PI3K/AKT pathway to induce EMT in melanoma cells." (PMID 36268276, 2022). "Together, these results show that TRIP13 is highly expressed in melanoma and indicated poor prognosis of melanoma patients." (PMID 36268276, 2022). "MV3 and A2058 melanoma cells were transfected with lentiviral vector to overexpress or knockdown TRIP13 expression level, and then, its biological function was studied using a series of in vitro and in vivo assays." (PMID 36268276, 2022). "The results of this study exhibited that TRIP13 expression was upregulated in melanoma tissue compared with normal tissues, and high levels of TRIP13 were closely correlated with poor prognoses of melanoma patients." (PMID 36268276, 2022). "Then, we examined TRIP13 expression in our own melanoma cohort and found that the protein was localized in the cytoplasm of melanoma cells." (PMID 36268276, 2022). "The present study revealed that TRIP13 is a novel prognostic biomarker and potential therapeutic target for melanoma treatment." (PMID 36268276, 2022). "Univariate and multivariate analyses showed that high TRIP13 level was an independent predictor of poor prognosis in patients with melanoma." (PMID 36268276, 2022). "In view of this, we examined the expression and clinical significance of TRIP13 in tumor tissues of melanoma patients and investigated the biological function and mechanism of TRIP13 in melanoma." (PMID 36268276, 2022). "To further study the molecular mechanism of TRIP13, we performed immunoprecipitation (IP) and liquid chromatography tandem mass spectrometry (LC-MS/MS) to identify the TRIP13-interacting proteins in melanoma." (PMID 36268276, 2022). "In the present study, we found that TRIP13 also activates AKT signaling to promote melanoma malignant phenotypes which is consistent with the previous research; we further discovered that TRIP13 activates AKT signaling by directly interacting with FLNA." (PMID 36268276, 2022). "To investigate the biological function of TRIP13 in melanoma cells, we transfected TRIP13 shRNAs into MV3 cells and TRIP13 cDNA vectors into A2058 cells." (PMID 36268276, 2022). "In conclusion, the results of this study demonstrate the important role of TRIP13 in promoting melanoma progression and EMT via the FLNA/PI3K/AKT pathway." (PMID 36268276, 2022). "We found that TRIP13 was significantly upregulated in melanoma compared to adjacent normal tissue, and it was strongly correlated with poor prognosis in melanoma patients." (PMID 36268276, 2022). "In the TCGA-SKCM dataset, we found that TRIP13 mRNA level was higher in melanoma than in normal skin, and elevated TRIP13 was correlated with poor prognosis of melanoma patients." (PMID 36268276, 2022). "Elevated TRIP13 promoted the invasion and migration of melanoma cells in vitro and enhanced lung metastasis in vivo, without an influence on tumor growth." (PMID 36268276, 2022). "To elucidate the mechanism of TRIP13-induced tumor progression, we performed RNA sequencing on melanoma cells with different TRIP13 expression." (PMID 36268276, 2022). "Among these differentially expressed genes, thyroid hormone receptor interactor 13 (TRIP13) has been reported to exert an important role in the development of various tumors, while its role in melanoma remains unclear." (PMID 36268276, 2022). "Importantly, univariate and multivariate analyses showed that elevated TRIP13 expression was an independent predictor of unfavorable melanoma prognosis." (PMID 36268276, 2022). "One of these genes, TRIP13, which has a role in melanoma remains unclear was selected for further study." (PMID 36268276, 2022).
melanoma (continued). "Additionally, to detect the role of FLNA in TRIP13-induced melanoma progression, we performed a series of rescue assays." (PMID 36268276, 2022). "Moreover, the Kaplan-Meier analyses showing patients with higher expression of TRIP13 and FLNA had reduced OS and DFS than other patients; it indicates that TRIP13 combined with FLNA can be an effective indicator to predict prognosis in melanoma patients." (PMID 36268276, 2022). "Importantly, elevated TRIP13 promoted the epithelial-mesenchymal transition (EMT) of melanoma cells, indicating a higher metastatic potential of these cells." (PMID 36268276, 2022). "Additionally, to explore the clinical value of TRIP13, we divided these 123 melanoma patients into two groups according to the expression of TRIP13." (PMID 36268276, 2022). "To confirm the interaction between TRIP13 and FLNA, we performed immunofluorescence assays and confirmed that TRIP13 and FLNA colocalized in melanoma cells." (PMID 36268276, 2022). "We next validated the relationship between TRIP13 and FLNA expression in tissue specimens of melanoma patients." (PMID 36268276, 2022). "However, the detailed function of TRIP13 in melanoma progression remains unclear." (PMID 36268276, 2022). "co-IP assays further confirmed the physical interaction of TRIP13 and FLNA in melanoma cells." (PMID 36268276, 2022). "Together, we propose a model in which TRIP13 activates the PI3K/AKT signaling to transcriptional activation of N-cadherin and inhibition of E-cadherin through the interaction with FLNA and then induces melanoma cell migration, invasion, and EMT." (PMID 36268276, 2022). "ACSL3 was coexpressed with SNUPN, TRIP13, and SEMA5A in melanoma." (PMID 27171439, 2016). "Interestingly, in the 57,490,258–58,411,259 pb region of chromosome 21 associated with two traits (VM and VN), we found five candidate genes (LPCAT1, CLPTM1L, TERT, TRIP13, and BRD9), all of which were related to the main types of skin cancer, i.e., melanoma and cutaneous squamous cell carcinoma." (PMID 39199954, 2024). "Therefore, we speculated that TRIP13 exerted the role of the PI3K/AKT pathway activation and EMT of melanoma cells through interaction with FLNA." (PMID 36268276, 2022). "However, elevated TRIP13 expression did not influence the tumor growth of melanoma in vivo." (PMID 36268276, 2022).
chronic lymphocytic leukemia (3 papers, 2017 to 2022). "A study displayed that knocking down TRIP13 can inhibit the cell proliferation of human chronic lymphocytic leukemia." (PMID 35601150, 2022).
clear cell renal cell carcinoma (3 papers, 2021 to 2025). "High TRIP13 expression has been shown to reveal poor course in other carcinomas such as renal renal clear cell carcinoma, renal papillary cell carcinoma, brain low grade glioma, liver hepatocellular carcinoma in total survival (OS: overall survival) analysis." (PMID 33237662, 2021).
glioma (3 papers, 2021 to 2025). A benign or malignant brain and spinal cord tumor that arises from glial cells (astrocytes, oligodendrocytes, ependymal cells). "The aberrant expression of TRIP13 in gliomas was uncovered to be regulated by distinct underlying mechanisms, including the DNA methylation and dysfunction of miRNA targeting (such as miR-29 family)." (PMID 34066132, 2021). "The GSE16011 data indicated that increased TRIP13 levels in all grade and lower-grade glioma patients were predominantly associated with poor overall survival time (OS)." (PMID 34066132, 2021). "Additional pathways significantly associated with TRIP13 expression in glioma included “G2/M DNA damage checkpoint” (p = 2.34 × 10−9) and “ATM signaling” (p = 2.95 × 10−7)." (PMID 34066132, 2021). "High expression of TRIP13 is associated with IDH-wild type gliomas." (PMID 34066132, 2021). "Therefore, we speculated that the reduced expression levels of miR-29s are significantly associated with the regulation of TRIP13 in glioma." (PMID 34066132, 2021). "To clarify the role of TRIP13 in glioma, we firstly identified the gene strongly correlated with TRIP13 across the three independent datasets (TCGA, CGGA and GSE16011) by Pearson correlation analysis (Pearson R > 0.6)." (PMID 34066132, 2021). "The study aimed to provide comprehensive information about the oncogenic potential of TRIP13 in clinical significance for gliomas." (PMID 34066132, 2021). "We also found that the mRNA expression levels of TRIP13 were elevated in higher–grade glioma patients in microarray data (also validated by mRNA and protein assay) and demonstrated significantly poor prognosis in LGG and GBM patients from TCGA and CGGA data." (PMID 34066132, 2021). "In this study, we were interested to investigate the relevance between TRIP13 expression and tumor aneuploidy patterns with influence on immune signaling in glioma." (PMID 34066132, 2021). "In the TCGA database, high-grade glioma showed higher expression of TRIP13 compared with low-grade glioma." (PMID 34066132, 2021). "The significantly negative correlations were shown between mir-29a (r = −0.287, p = 2.17 × 10−11), mir-29b (r = −0.273, p = 1.94 × 10−10), mir-29c (r = −0.322, p = 4.15 × 10−14) and TRIP13 in low-grade glioma." (PMID 34066132, 2021). "Thyroid Receptor Interacting Protein 13 (TRIP13) was found to be overexpressed in several solid tumors, but its role and clinical significance in gliomas is still unclear." (PMID 34066132, 2021). "Then, TCGA analysis revealed that more TRIP13 promoter hypomethylation was observed in GBM than in low-grade glioma." (PMID 34066132, 2021). "We initially uncovered the prognostic features of TRIP13 by series expression analysis of glioma using numerous cohort data." (PMID 34066132, 2021). "In vitro experiments demonstrated that TRIP13 mRNA expression was notably higher in glioma cells compared to normal brain tissue, and its proteins were highly produced in human glioma cell lines." (PMID 34066132, 2021). "This open resource allowed the standardized mRNA expression of TRIP13 in normal brain and glioma tissues to be obtained." (PMID 34066132, 2021). "Our findings are the first to uncover the novel function of TRIP13 and suggest a new linkage between TRIP13 and immune components in low- and high-grade glioma." (PMID 34066132, 2021). "In this study, we present the oncogene, TRIP13 to in-depth investigation of its expression and prognostic features as well as its novel correlation with aneuploidy and immune modulation in glioma microenvironment by integrative multi-omics analysis." (PMID 34066132, 2021). "The genes co-expressed with TRIP13 identified using the three glioma related datasets were subjected to functional and pathway enrichment analyses." (PMID 34066132, 2021). "In summary, our data revealed that high TRIP13 expression was closely correlated with worse outcomes in low- and high-grade glioma." (PMID 34066132, 2021).
glioma (continued). "Our study showed that expression of TRIP13 is higher in wild type IDH than in mutant-type IDH in lower-grade glioma." (PMID 34066132, 2021). "The DNA methylation profiles of the TRIP13 gene appear to be differing between low-grade glioma and GBM according to the data visualization." (PMID 34066132, 2021). "The network by 10 circRNAs which were predicted to sponge miR-29s identified by glioma samples in human circRNA database, as well as miR-29s and TRIP13, were firstly built in this study." (PMID 34066132, 2021). "In spite of this, these data still suggest that TRIP13 expression is a poor prognostic factor for lower-grade glioma and GBM patients." (PMID 34066132, 2021). "It reflected that the over-expressed TRIP13 may potentially participate in the molecular mechanism connecting the generation or maintenance of aneuploidy in glioma." (PMID 34066132, 2021). "Lower-grade glioma with IDH-wild type expressed high TRIP13 levels in TCGA and CGGA data." (PMID 34066132, 2021). "In this study, we demonstrated for the first time that TRIP13 may be potentially related to recurrence of glioma in patients." (PMID 34066132, 2021). "The inverse correlation between the expressions of TRIP13 and miR-29a/b/c was observed in our study, implying that downregulation of miR-29s may lead to over-expressed TRIP13 in gliomas." (PMID 34066132, 2021). "We provided multi-level evidence to demonstrate the diverse function of TRIP13 in glioma." (PMID 34066132, 2021). "Therefore, we inferred that TRIP13 and its co-expressed genes jointly regulate glioma tumorigenesis and progression through a complicated regulatory network." (PMID 34066132, 2021). "Overall, these findings demonstrate that TRIP13 has with multiple functions in gliomas, and they may be crucial for therapeutic potential." (PMID 34066132, 2021). "We also inferred that the upregulated TRIP13 levels in gliomas could be regulated by dysfunction of miR-29 in gliomas patient cohorts." (PMID 34066132, 2021). "This inspired us to explore whether high expression of TRIP13 in glioma (significantly high aneuploidy populations) to be implicated in abnormalities of immune system." (PMID 34066132, 2021). "However, the biological role and clinical significance of TRIP13 in human glioma remains poorly elucidated." (PMID 34066132, 2021). "Moreover, TRIP13 was negatively correlated with overall survival and progression-free survival time in different grade of glioma patients, implying TRIP13 could be an oncogenic factor in the disease." (PMID 34066132, 2021). "Finally, the TCGA analysis revealed that TRIP13 mRNA expression was positively correlated with glioma aneuploidy and may potentially modulate immune cell populations in the microenvironment." (PMID 34066132, 2021). "Similar survival trends were observed for TRIP13 and SHLD1 expression in low grade glioma patients receiving TMZ." (PMID 38906885, 2024). "Then, we evaluated the relationship between expression of TRIP13 and the WHO grading system of glioma." (PMID 34066132, 2021). "A further finding is that these immune signatures were downregulated both in low-grade glioma and GBM with TRIP13 overexpression." (PMID 34066132, 2021). "Gene expression profiles of the Cancer Genome Atlas (TCGA), Chinese Glioma Genome Atlas (CGGA) and GSE16011 dataset showed increased TRIP13 expression in advanced stage and worse prognosis in IDH-wild type lower-grade glioma." (PMID 34066132, 2021). "In this study, we screened the Cancer Genome Atlas (TCGA), Chinese Glioma Genome Atlas (CGGA) and GSE16011 datasets and found that TRIP13 mRNA expression elevated in advanced grade of gliomas and isocitrate dehydrogenase 1 wild type (IDH1-WT) in lower-grade glioma." (PMID 34066132, 2021). "Based on these results, it is suggested that TRIP13 may play a potential role in the regulation of CD8+ and Treg cells in the tumor microenvironment between different grades of glioma." (PMID 34066132, 2021).
glioma (continued). "Indeed, we found a close correlation between TRIP13 and Plk1 (r = 0.7016, p < 10−15) in GBM, which provides for the rational development of new targeted therapies for glioma." (PMID 34066132, 2021). "We also investigated the progression-free survival (PFS) of these groups in TCGA, and found that all grade and lower-grade glioma patients with high TRIP13 levels showed shorter PFS, but this was not significant in GBM patients." (PMID 34066132, 2021). "Moreover, FOXM1 and HMMR genes, which promote stemness of glioma stem cells (GSC), resistant to apoptosis induced by oxidative stress and chemotherapy and regulation of tumor metastasis, are detected co-localized with TRIP13 gene." (PMID 34066132, 2021).
head and neck squamous cell carcinoma (3 papers, 2022 to 2025). A squamous cell carcinoma that arises from any of the following anatomic sites: lip and oral cavity, nasal cavity, paranasal sinuses, pharynx, larynx, and salivary glands. "In the previous research, TRIP13 could promote drug resistance to head and neck squamous cell carcinoma by enhancing the repair effect of DNA damage." (PMID 35601150, 2022). "Researchers found that TRIP13 could promote the DSB repair of head and neck squamous cell carcinoma cells through NHEJ, resulting in drug resistance." (PMID 35601150, 2022). "It has also been reported that head and neck squamous cell carcinoma (HNSCC) cells overexpressing TRIP13 are resistant to chemotherapy and radiation." (PMID 35204785, 2022).
lymphoma (3 papers, 2021 to 2024). A malignant (clonal) proliferation of B- lymphocytes or T- lymphocytes which involves the lymph nodes, bone marrow and/or extranodal sites. "Altogether we show that human PTCL are characterized by a large number of recurrent methylation alterations affecting the expression of genes involved in tumorigenesis and functionally demonstrate that TRIP13 plays a role in PTCL lymphoma maintenance in vitro." (PMID 38464090, 2024). "To test if targeting TRIP13 may have therapeutic potential, we next treated lymphoma cell lines with DCZ0415, a TRIP13-specific inhibitor." (PMID 39189258, 2024).
osteosarcoma (3 papers, 2012 to 2024). A usually aggressive malignant bone-forming mesenchymal neoplasm, predominantly affecting adolescents and young adults. "We first studied the effect of Trip13 KD in the osteosarcoma cell line U2OS." (PMID 36031387, 2022). "In the literature, a gain of 5p has been found in osteosarcoma and malignant fibrous histiocytoma, and studies combining aCGH and gene expression assays suggest that 5pter-p15.3 harbors several candidate oncogenes including TRIP13, TERT, NDUFS6, and ADAMT16." (PMID 22551002, 2012).
pancreatic cancer (3 papers, 2017 to 2025). "Bioinformatics, datamining, transcriptomics, and molecular biology techniques were utilized to demonstrate the role of TRIP13 pancreatic cancer pathobiology and pancreatic cancer progression." (PMID 38074464, 2023). "In this study, the potential role of TRIP13 in pancreatic cancer is decoded by using an integrated computational biology and wet lab experimental approaches." (PMID 38074464, 2023). "•This study elucidates the role of TRIP13 on molecular level, as a specific signal for early events of pancreatic cancer, enhancing patient prognosis, and boosting targeted therapies in clinical settings." (PMID 38074464, 2023). "Results of this study suggest that TRIP13 may be involved in early events of pancreatic cancer, thus, it might be a useful molecular signature for advancing early detection and therapeutics of pancreatic cancer." (PMID 38074464, 2023). "Other wet lab experimentations demonstrate the expression of TRIP13 as a specific signal for early events of pancreatic cancer, this proper positioning may enhance patient prognosis, and boosting targeted therapies in clinical settings." (PMID 38074464, 2023). "However, studies in a larger patient cohort and in-depth basic mechanistic studies will provide next level information to further understand the biological implications of TRIP13 in pancreatic cancer and this study will pave a strong pathway for future studies on TRIP13." (PMID 38074464, 2023).